NCOA1 (nuclear receptor coactivator 1)
Description:
Nuclear receptor coactivator that directly binds nuclear receptors and stimulates the transcriptional activities in a hormone-dependent fashion. Involved in the coactivation of different nuclear receptors, such as for steroids (PGR, GR and ER), retinoids (RXRs), thyroid hormone (TRs) and prostanoids (PPARs). Also involved in coactivation mediated by STAT3, STAT5A, STAT5B and STAT6 transcription factors. Displays histone acetyltransferase activity toward H3 and H4; the relevance of such activity remains however unclear. Plays a central role in creating multisubunit coactivator complexes that act via remodeling of chromatin, and possibly acts by participating in both chromatin remodeling and recruitment of general transcription factors. Required with NCOA2 to control energy balance between white and brown adipose tissues. Required for mediating steroid hormone response. Isoform 2 has a higher thyroid hormone-dependent transactivation activity than isoform 1 and isoform 3.
Synonyms: NCoA-1; bHLHe74; SRC1; F-SRC-1; KAT13A; RIP160; bHLHe42
Tractability: Small molecule: a structure with a bound ligand is known; a high-quality ligand is known; it has a high-quality binding pocket. Antibody: its Gene Ontology location is reachable by antibodies, with high confidence; the Human Protein Atlas places it where antibodies can reach. PROTAC: UniProt records ubiquitination sites on it; ubiquitination databases record sites on it; its protein half-life has been measured; a small molecule that binds it is known.
Target class: SRC family; Epigenetic regulator; Histone acetyltransferase; Writer
Safety:
Unwanted effects reported when the protein is acted on. In parentheses: how it was acted on, where the effect was seen, and who reports it.
decrease in bone mineral density (source: ClinPGx)
less of a decrease in bone mineral density (source: ClinPGx)
Gene: Protein-coding gene on chromosome 2 (24,490,992 to 24,770,702, forward strand). Ensembl gene ENSG00000084676.
Subcellular location: Nucleus
Subcellular location (Human Protein Atlas): Cytosol; Nucleoplasm; Plasma membrane; Vesicles
Pathways (Reactome):
Metabolism: Activation of gene expression by SREBF (SREBP); Endogenous sterols; PPARA activates gene expression; Recycling of bile acids and salts; Regulation of lipid metabolism by PPARalpha; Synthesis of bile acids and bile salts; Synthesis of bile acids and bile salts via 27-hydroxycholesterol; Synthesis of bile acids and bile salts via 7alpha-hydroxycholesterol
Circadian clock: BMAL1:CLOCK,NPAS2 activates circadian expression; Expression of BMAL (ARNTL), CLOCK, and NPAS2; RORA,B,C and NR1D1 (REV-ERBA) regulate gene expression
Signal Transduction: Estrogen-dependent gene expression; NR1H2 & NR1H3 regulate gene expression to control bile acid homeostasis; NR1H3 & NR1H2 regulate gene expression linked to cholesterol transport and efflux
Cellular responses to stimuli: Cytoprotection by HMOX1; Heme signaling
Developmental Biology: Transcriptional regulation of brown and beige adipocyte differentiation by EBF2; Transcriptional regulation of white adipocyte differentiation
Chromatin organization: HATs acetylate histones
Gene expression (Transcription): MLL4 and MLL3 complexes regulate expression of PPARG target genes in adipogenesis and hepatic steatosis
Metabolism of proteins: SUMOylation of transcription cofactors
Organelle biogenesis and maintenance: Transcriptional activation of mitochondrial biogenesis
Gene Ontology:
Molecular function: nuclear estrogen receptor binding; nuclear receptor binding; protein binding; transcription coactivator activity; transcription coregulator activity; chromatin binding; DNA binding; nuclear retinoic acid receptor binding; nuclear retinoid X receptor binding; protein dimerization activity; protein-containing complex binding; protein-lysine-acetyltransferase activity; RNA polymerase II transcription regulatory region sequence-specific DNA binding
Biological process: estrogen receptor signaling pathway; mRNA transcription by RNA polymerase II; positive regulation of DNA-templated transcription; positive regulation of transcription by RNA polymerase II; positive regulation of transcription from RNA polymerase II promoter by galactose; progesterone receptor signaling pathway; bile acid and bile salt transport; cellular response to hormone stimulus; peroxisome proliferator activated receptor signaling pathway; positive regulation of adipose tissue development; regulation of cellular response to insulin stimulus; cerebellum development; cerebral cortex development; estrous cycle; hippocampus development; hypothalamus development; lactation; male gonad development; male mating behavior; positive regulation of apoptotic process; positive regulation of female receptivity; positive regulation of neuron differentiation; regulation of DNA-templated transcription; response to estradiol; response to hormone; and 2 more
Cellular component: chromatin; protein-containing complex; RNA polymerase II transcription regulator complex; transcription regulator complex; nucleoplasm; nucleus
Genetic constraint (gnomAD): Loss-of-function variants: 30 observed, 136.63 expected, observed/expected ratio (o/e) 0.22, 90% interval 0.16 to 0.3. The upper end of that interval is the gene's LOEUF score, 0.3, which puts it in group 1 of 6, group 1 being the genes least tolerant of losing a copy. Missense variants: 1,382 observed, 1,671.7 expected, observed/expected ratio (o/e) 0.83, 90% interval 0.79 to 0.86. Synonymous variants: 546 observed, 604.83 expected, observed/expected ratio (o/e) 0.9, 90% interval 0.84 to 0.97.
Homologues: Orthologues: chimpanzee NCOA1 (99% identical), macaque NCOA1 (99% identical), pig NCOA1 (97% identical), dog NCOA1 (96% identical), rabbit NCOA1 (95% identical), guinea pig NCOA1 (94% identical), rat Ncoa1 (94% identical), mouse Ncoa1 (89% identical), tropical clawed frog ncoa1 (67% identical), zebrafish ncoa1 (45% identical), Drosophila melanogaster tai (20% identical). Paralogues in human: NCOA2 (36% identical), NCOA3 (32% identical).
Diseases named in the same sentence as NCOA1 in open-access papers:
NCOA1 is named in the same sentence as 70 diseases in open-access papers, as found by Europe PMC text mining. Sharing a sentence is not in itself a finding about the gene and the disease. The quoted sentences say what the papers report.
breast cancer (30 papers, 2004 to 2026). A primary or metastatic malignant neoplasm involving the breast. "NCOA1 is known as the “master regulator” of the steroid hormone receptors: estrogen receptor and androgen receptor, which are implicated in breast cancer progression." (PMID 36248436, 2022). "The minor allele of rs13035764 in the NCOA1 was associated with an enhanced risk of breast cancer for younger age at menarche in the SEBCS." (PMID 34069208, 2021). "In this study, we discovered that Ncoa1 protein levels are positively associated with the densities of small blood vessels in several models of mouse mammary tumors induced by PyMT or Neu (HER2) expression." (PMID 26287601, 2015). "Moreover, NCOA1 is recruited to the VEGFa promoter by associating with HIF1α and c-Fos in breast cancer cells." (PMID 26287601, 2015). "However, the specific role of NCOA1 in breast tumor angiogenesis, the hallmark of breast cancer progression to metastasis, remains to be defined." (PMID 26287601, 2015). "Because of the critical importance of coregulators for ERα function, we hypothesized that breast cancer risk is influenced by SNPs within the coactivators SRC-1/NCoA1 and SRC-3/NCoA3/AIB1 and the corepressors NCoR and SMRT/NCoR2." (PMID 20003447, 2009). "The members of the miR-23a ~ 27a ~ 24-2 cluster integrally inhibit the aggressiveness of breast cancer cells by targeting NCOA1, NLK, and RAP1B." (PMID 39112518, 2024). "The overexpression of nuclear receptor coactivator 1 (NCOA1) has also shown a positive correlation with disease metastasis and recurrence that resides in a subset of breast cancers." (PMID 33593445, 2021). "The pathway analysis also clarifies the role of NCOA1 in proliferation and metastasis of breast cancer by interaction with these proteins." (PMID 33593445, 2021). "The gene mapping of 24 DEGs through PubMed, OMIM, MeSH, and PMC databases provided eight significant breast cancer associated genes: ID4, NCOA1, RHEB, PDZK1, PLAUR, AKC1R2, ANXA1 and SLIPI." (PMID 33593445, 2021). "NCOA1 has been found to potentiate the roles of estrogen receptor (ER) and mediate transcription reprogramming in ER-positive breast cancer cells." (PMID 30941313, 2019). "Together, our results define an NCOA1/ ___?___ /CSF1 regulatory axis that promotes breast cancer metastasis, offering a novel therapeutic target for impeding this process." (PMID 29305341, 2018). "The most widely studied steroid receptor coactivator family in breast cancer are the p160 kDa group of SRC −1 (NCOA1), −2(NCOA2), and −3 (NCOA3/AIB1)." (PMID 30416486, 2018). "Such ligands induced breast cancer cell proliferation in a manner that was predicted by the canonical recruitment of the coactivators NCOA1/2/3 and induction of the GREB1 proliferative gene." (PMID 27107013, 2016). "Nuclear receptor coactivator 1 (NCOA1) is overexpressed in a subset of breast cancer and its increased expression positively correlates with disease recurrence and metastasis." (PMID 26287601, 2015). "NCOA1 protein was mainly detected in the nuclei of breast cancer cells at different immunostaining intensities in different tumor sections." (PMID 26287601, 2015). "First, we showed that the compromised ability of Ncoa1 null mammary tumor cells to induce in vivo angiogenesis can be rescued by VEGFa treatment, suggesting a reduced secretion of VEGFa from Ncoa1 null cells." (PMID 26287601, 2015). "Together, these results demonstrate that the level of Ncoa1 expression positively correlates with MVD in all three different mouse breast cancer models." (PMID 26287601, 2015). "We found that VEGFa mRNA expression is 5 and 3 fold lower in K1 and K2 Ncoa1 knockout mouse mammary tumor cells than that in W1 and W2 Ncoa1 WT mouse mammary tumor cells, respectively." (PMID 26287601, 2015).
breast cancer (continued). "Semi-quantitative analysis revealed that MVD is reduced 70% and 60% in Ncoa1 knockout (Ncoa1−/−) mammary tumors versus Ncoa1 wild type (Ncoa1+/+) mammary tumors at week 8 and week 13 after the detection of palpable tumors in Tg(MMTV-PyMT) mice." (PMID 26287601, 2015). "Together, the consensus of these results indicates that VEGFa expression levels positively correlate with Ncoa1 expression levels in multiple breast cancer mouse models." (PMID 26287601, 2015). "Our co-immunoprecipitation assay also demonstrated that NCOA1 forms a protein complex with HIF1α in MDA-MB-231 breast cancer cells." (PMID 26287601, 2015). "Consistently, MVD is remarkably increased in the mammary tumors with transgenic NCOA1 overexpression in Tg(MMTV-NCOA1) × Tg(MMTV-TVA/RCAS-PyMT) mice versus mammary tumors with normal Ncoa1 expression in Tg(MMTV-TVA/RCAS-PyMT) mice." (PMID 26287601, 2015). "Consistently, we have previously shown that NCOA1 overexpression in the mouse mammary tumor cells significantly promoted lung metastasis, while knockout of Ncoa1 in the mouse tumor cells drastically inhibited lung metastasis." (PMID 26287601, 2015). "In this study, we report that NCOA1 works with transcription factors HIF1α and AP-1 (c-Jun/c-Fos) to promote VEGFα expression in breast cancer cells and drive breast tumor angiogenesis in both mouse and human breast tumors." (PMID 26287601, 2015). "Knockdown of NCOA1 using two different shRNAs in MDA-MB-231 human breast cancer cells also drastically reduced both VEGFa mRNA expression and VEGFa protein secreted into the culture medium." (PMID 26287601, 2015). "In this study, we found that the microvascular density (MVD) was significantly decreased and increased in Ncoa1-knockout and NCOA1-overexpressing mammary tumors, respectively, in several breast cancer mouse models." (PMID 26287601, 2015). "Although NCOA1 is known to promote breast cancer metastasis through working with multiple transcription factors to upregulate the expression of Twist1, ITGA5, CSF-1, SDF1 and CXCR4, the role of NCOA1 in breast tumor angiogenesis has not been investigated." (PMID 26287601, 2015). "For example, the coactivator NCOA1 is highly expressed in endometrial cancer cells, but is present in low levels in breast cancer cells." (PMID 22163294, 2011). "In addition, four genes CCND1, ESR1, STAT3, and NCOA1 were enriched for mammary neoplasms, experimental (C0024668)." (PMID 34504716, 2021). "NCOA1 has previously been reported to be overexpressed in breast cancer and its increased expression positively correlated with disease recurrence and metastasis through working with multiple transcription factors to, in turn, upregulate the expression of Twist1, ITGA5, CSF-1, SDF1 and CXCR4." (PMID 28060733, 2017). "Furthermore, we demonstrated that knockout of Ncoa1 in mouse mammary tumor cells or knockdown of NCOA1 in human breast cancer cells largely compromised their capabilities to induce angiogenesis in vivo." (PMID 26287601, 2015). "To explore the relationship between Ncoa1 expression and mammary tumor angiogenesis, we examined MVD in mammary tumors developed in three previously established mouse models with normal Ncoa1, Ncoa1 knockout or NCOA1 overexpression by immunostaining CD31, a molecular marker of endothelial cells." (PMID 26287601, 2015). "Our findings suggest that NCOA1-promoted breast cancer metastasis may be related to its role in angiogenesis and thus NCOA1 may serve as a new molecular target for inhibiting breast tumor angiogenesis and metastasis." (PMID 26287601, 2015). "Knockout or knockdown of NCOA1 in breast cancer cell lines also markedly compromised their capability to induce angiogenesis in Matrigel plugs embedded subcutaneously in mice, while this compromised capability could be rescued by VEGFa treatment." (PMID 26287601, 2015).
breast cancer (continued). "NCOA1 works not only with both HIF1α and AP-1 to upregulate VEGFa expression as shown in this study but also works with different transcription factors to upregulate different target genes to promote breast cancer progression and metastasis." (PMID 26287601, 2015). "Indeed, global gene repression by NCoA1 promotes oncogenesis and metastatic spread in breast cancer." (PMID 26244872, 2015). "In summary, this study revealed a novel mechanism that NCOA1 potentiates breast cancer angiogenesis through upregulating HIF1α and AP-1-mediated VEGFa expression, which reinforces the rational of targeting NCOA1 in controlling breast cancer progression and metastasis." (PMID 26287601, 2015). "Thus, we set out to identify novel single nucleotide polymorphisms (SNPs) within SRC-1 (NCoA1), SRC-3 (NCoA3, AIB1), NCoR (NCoR1), and SMRT (NCoR2), and test the most promising SNPs for associations with breast cancer risk." (PMID 20003447, 2009). "Furthermore, MVD is also significantly increased in NCOA1-overexpressing mammary tumors in Tg(MMTV-NCOA1) × Tg(MMTV-Neu) mice versus mammary tumors with normal Ncoa1 expression in Tg(MMTV-neu) mice at both week 2 and week 9 after the detection of palpable tumors." (PMID 26287601, 2015). "Therefore, NCOA1 overexpression-induced angiogenesis in breast tumors may directly contribute to breast cancer progression and metastasis." (PMID 26287601, 2015). "While the functions of NCOA1 and NCOA3 have been widely explored in breast cancer, little is known about the biological roles of NCOA2 in regulating genes involved in breast cancer progression." (PMID 30941313, 2019). "Completely blocking AF‐2 with an extended side chain or altering the shape of AF‐2 changes the preference away from NCOA1/2/3 for determining GREB1 levels and proliferation of breast cancer cells." (PMID 27107013, 2016). "In the canonical model of the ERα signaling pathway, E2‐bound ERα forms a homodimer that binds DNA at estrogen‐response elements (EREs), recruits NCOA1/2/3, and activates the GREB1 gene, which is required for proliferation of ERα‐positive breast cancer cells." (PMID 27107013, 2016). "Recently, gossypol and bufalin have been identified as specific small molecular inhibitors for both NCOA1 and NCOA3 and have been shown to inhibit breast cancer cell growth and/or metastasis in culture and/or mice." (PMID 26287601, 2015). "These translational studies suggest that targeting these overexpressed coactivators like NCOA1 and NCOA3 is indeed a feasible approach to control breast cancer growth and/or metastasis." (PMID 26287601, 2015). "Applying quantitative real-time RT-PCR (qRT-PCR), Western Blot analysis and chromatin immunoprecipitation, we analyzed the involvement of NCOA1, NCOA2, NCOA3 in the ERα-mediated transactivation of PLAC1 in the breast cancer cell lines MCF-7 and SK-BR-3." (PMID 24304549, 2013). "Gene amplification and overexpression of NCOA1, NCOA2 and NCOA3 in breast cancer has been described previously by several groups thus contributing to the development of cancer." (PMID 24304549, 2013). "The combination of NCOA1 and the transcription factor HOXC11 can activate the transcription of downstream genes, including integrin α5, ADAM22, and Myc, and can thus promote the metastasis and progression of breast cancer." (PMID 37509133, 2023). "To identify potential angiogenic factors regulated by Ncoa1, we measured the expression levels of many angiogenic factors in mouse mammary tumor cells that either have no functional Ncoa1 or have different levels of Ncoa1." (PMID 26287601, 2015). "Inversely, knockout of Ncoa1 remarkably inhibits lung metastasis without affecting primary mammary tumor growth in Tg(MMTV-PyMT) mice." (PMID 26287601, 2015).
breast cancer (continued). "We detected selective recruitment of NCOA3 but not NCOA1 or NCOA2 to the PLAC1 promoter only in ERα-positive MCF-7 cells but not in ERα-negative SK-BR-3 breast cancer cells." (PMID 24304549, 2013). "The higher expression of NCOA1 allows tamoxifen to act as an ERα agonist in endometrial cancer, but not in breast cancer cells." (PMID 22163294, 2011). "However, we found that although NCOA1 promotes angiogenesis in breast tumors, overexpression or knockout of Ncoa1 in mice does not significantly affect mammary tumor growth." (PMID 26287601, 2015). "Furthermore, the expression level of VEGFa mRNA, but not VEGFc mRNA, is increased more than 3 folds in NCOA1-overexpressing mammary tumors in Tg(MMTV-NCOA1) × Tg(MMTV-TVA/RCAS-PyMT) mice when compared with that in Ncoa1 WT mammary tumors in Tg(MMTV-TVA/RCAS-PyMT) mice." (PMID 26287601, 2015). "In a first experiment, we analyzed expression of NCOA1, NCOA2 and NCOA3 in ERα-positive MCF-7 and ERα-negative SK-BR-3 breast cancer cells that both have been shown to express PLAC1 protein." (PMID 24304549, 2013).